RRAGB (Ras related GTP binding B)
Description:
Guanine nucleotide-binding protein that plays a crucial role in the cellular response to amino acid availability through regulation of the mTORC1 signaling cascade. Forms heterodimeric Rag complexes with RagC/RRAGC or RagD/RRAGD and cycles between an inactive GDP-bound and an active GTP-bound form: RagB/RRAGB is in its active form when GTP-bound RagB/RRAGB forms a complex with GDP-bound RagC/RRAGC (or RagD/RRAGD) and in an inactive form when GDP-bound RagB/RRAGB heterodimerizes with GTP-bound RagC/RRAGC (or RagD/RRAGD). In its GTP-bound active form, promotes the recruitment of mTORC1 to the lysosomes and its subsequent activation by the GTPase RHEB. Involved in the RCC1/Ran-GTPase pathway.
Synonyms: RagB; bA465E19.1
Tractability: PROTAC: UniProt records ubiquitination sites on it; ubiquitination databases record sites on it; its protein half-life has been measured.
Gene: Protein-coding gene on chromosome X (55,717,743 to 55,758,774, forward strand). Ensembl gene ENSG00000083750.
Subcellular location: Cytoplasm; Lysosome membrane
Subcellular location (Human Protein Atlas): Golgi apparatus; Vesicles
Pathways (Reactome):
Signal Transduction: Energy dependent regulation of mTOR by LKB1-AMPK; MTOR signalling; Regulation of PTEN gene transcription; mTORC1-mediated signalling
Autophagy: Macroautophagy
Cellular responses to stimuli: Amino acids regulate mTORC1
Gene Ontology:
Molecular function: GTP binding; GTPase activity; GTPase binding; guanyl ribonucleotide binding; protein binding
Biological process: cellular response to amino acid starvation; cellular response to amino acid stimulus; cellular response to leucine starvation; intracellular protein localization; positive regulation of TOR signaling; positive regulation of TORC1 signaling; regulation of TOR signaling; cellular response to starvation; negative regulation of autophagy
Cellular component: cytoplasm; Gtr1-Gtr2 GTPase complex; lysosomal membrane; lysosome; cytosol; nucleus
Homologues: Orthologues: chimpanzee RRAGB (100% identical), macaque RRAGB (99% identical), pig RRAGB (99% identical), mouse Rragb (97% identical), rat RragB (97% identical), guinea pig RRAGB (93% identical), rabbit RRAGB (92% identical), dog RRAGB (90% identical), zebrafish rraga (79% identical), Drosophila melanogaster RagA-B (69% identical), Caenorhabditis elegans raga-1 (58% identical). Paralogues in human: RRAGA (89% identical), RRAGC (26% identical), RRAGD (25% identical).
Diseases named in the same sentence as RRAGB in open-access papers:
RRAGB is named in the same sentence as 22 diseases in open-access papers, as found by Europe PMC text mining. Sharing a sentence is not in itself a finding about the gene and the disease. The quoted sentences say what the papers report.
colorectal cancer (3 papers, 2022 to 2025). A primary or metastatic malignant neoplasm that affects the colon or rectum. "circEXOC6B associates with RRAGB to antagonize HIF1A-RRAGB-mTORC1 positive feedback loop for enhancing 5-fluorouracil-induced apoptosis and repressing colorectal cancer growth." (PMID 40651979, 2025). "In colorectal cancer, circEXOC6B can bind to an mTORC1 activator, RRAGB, reduced tumor progression via antagonization of HIF1A/RRAGB/mTORC1 loop." (PMID 38152652, 2023).
colon adenocarcinoma (2 papers, 2021 to 2024). "Their results uncovered that RRAGB could be a prognostic biomarker for colon adenocarcinoma in terms of overall survival that is related to MSI, TMB, and immunity." (PMID 38051091, 2024).
prostate carcinoma (1 paper, 2020). A carcinoma that arises from epithelial cells of the prostate gland. "In prostate cancer, genetic alterations in RRAGA and RRAGC genes that encode RAGA and RAGC respectively are uncommon, however RRAGB (encoding RAGB) is amplified in up to 7.7% of cases and RRAGD (encoding RAGD) deep deletion occurs in 6.5–14.4% of cases." (PMID 32630372, 2020).
tumor (6 papers, 2021 to 2024). "Xiao and colleagues showed that RRAGB expression was significantly associated with MSI, tumor mutational burden (TMB) and immunity." (PMID 38051091, 2024). "With the help of the Sangerbox website tools, we calculated the correlations between the RRAGB expression and tumor immune infiltration by means of the Spearman’s method." (PMID 34320917, 2021). "In our article, we calculated the correlations between the RRAGB expression and tumor immune infiltration by the spearman’s method and found that the RRAGB mRNA expression was markedly related to B cells, CD4 + T cells and Macrophage cells infiltration." (PMID 34320917, 2021). "In addition, RRAGB expression was found to be significantly associated with microsatellite instability (MSI), tumor mutational burden (TMB) and immunity." (PMID 34320917, 2021). "Moreover, we also employed GSE44076 dataset to validate the expression of RRAGB in normal and tumor COAD cells (P = 1.92e-07; N = 148; T = 98)." (PMID 34320917, 2021). "Therefore, a HIF1A-RRAGB-mTORC1 positive feedback loop exists in CRC to drive tumor progression, and circEXOC6B might antagonize the loop by binding to RRAGB." (PMID 35739524, 2022). "SCNA module provided the correlations between tumor immune infiltration levels among COAD and different somatic copy number alterations for RRAGB by the Wilcoxon rank-sum test." (PMID 34320917, 2021).
cancer (5 papers, 2019 to 2025). A tumor composed of atypical neoplastic, often pleomorphic cells that invade other tissues. "Currently, no studies have reported the definite roles of RRAGB in human cancers and it was the first time for us to comprehensively explore the expression of RRAGB and its impact on COAD." (PMID 34320917, 2021). "Currently, no articles have explored the roles of RRAGB gene in the occurrence and development of cancer." (PMID 34320917, 2021). "In the Cancer Cell Line Encyclopedia (CCLE), expression of FNIP2 and RRAGD, and to some extent RRAGC, but not RRAGA or RRAGB, correlates with MITF expression." (PMID 41275493, 2025).
adenocarcinoma (1 paper, 2019). A common cancer characterized by the presence of malignant glandular cells. "The expression levels of RRAGB, RSPH9, RPS6KL1, RXFP1, and RTL1 mRNA were significantly lower and the RRM2 mRNA level was significantly higher in the high-risk group than those in the low-risk group in NSCLC adenocarcinoma of GSE11969." (PMID 31886214, 2019). "This signature and the genes RRAGB, RSPH9, RPS6KL1, RXFP1, RRM2, and RTL1 included in this model are independent biomarkers for prediction of overall survival of NSCLC adenocarcinoma." (PMID 31886214, 2019). "Our six-gene prognostic signature for NSCLC adenocarcinoma include RRAGB, RSPH9, RPS6KL1, RXFP1, RRM2, and RTL1 genes which are not contained in the previous gene signatures." (PMID 31886214, 2019).
RRAGB also shares sentences with these, for which no sentence is quoted: periodontitis (3 papers); acute myeloid leukaemia (1); breast carcinoma (1); cardiomyopathy (1); cervical cancer (1); cyst (1); infection (1); intracerebral hemorrhage (1); lung adenocarcinoma (1); lung carcinoma (1); non-small cell lung carcinoma (1); ovarian carcinoma (1); periodontal disease (1); prostate adenocarcinoma (1); sarcoma (1); venous ulcers (1).